OR8H1 (olfactory receptor family 8 subfamily H member 1)
Description:
Odorant receptor.
Synonyms: OR11-180
Tractability: Antibody: UniProt places it where antibodies can reach, with medium confidence; UniProt predicts a signal peptide or a membrane-spanning region; its Gene Ontology location is reachable by antibodies, with medium confidence.
Gene: Protein-coding gene on chromosome 11 (56,288,462 to 56,292,254, reverse strand). Ensembl gene ENSG00000181693.
Subcellular location: Cell membrane
Pathways (Reactome):
Sensory Perception: Expression and translocation of olfactory receptors
Gene Ontology:
Molecular function: olfactory receptor activity; G protein-coupled receptor activity
Biological process: G protein-coupled receptor signaling pathway; sensory perception of smell; detection of chemical stimulus involved in sensory perception of smell
Cellular component: plasma membrane; membrane
Genetic constraint (gnomAD): Loss-of-function variants: 0 observed, 0.47 expected, observed/expected ratio (o/e) 0, 90% interval 0 to 1.84. That is too few expected variants to judge how well the gene tolerates losing a copy. Missense variants: 383 observed, 380.25 expected, observed/expected ratio (o/e) 1.01, 90% interval 0.93 to 1.1. Synonymous variants: 132 observed, 134.02 expected, observed/expected ratio (o/e) 0.98, 90% interval 0.85 to 1.14.
Homologues: Orthologues: rat Or8h10 (74% identical), mouse Or8h9 (74% identical), mouse Or8h10 (73% identical), rat Or8h10c (72% identical), rat Or8h9 (72% identical), mouse Or8h7 (72% identical), rat Or8h6 (72% identical), rat Or8h7 (72% identical), mouse Or8h6 (72% identical), mouse Or8h8 (72% identical), rat Or8h11 (71% identical), rat Or8h7b (70% identical). Paralogues in human: OR8H3 (89% identical), OR8H2 (87% identical), OR8I2 (58% identical), OR5F1 (53% identical), OR5B12 (52% identical), OR8U1 (51% identical), OR5A1 (51% identical), OR5B21 (51% identical), OR8U3 (51% identical), OR8D4 (50% identical), OR5AP2 (50% identical), OR8A1 (50% identical), and 84 more.
Diseases named in the same sentence as OR8H1 in open-access papers:
OR8H1 is named in the same sentence as 4 diseases in open-access papers, as found by Europe PMC text mining. Sharing a sentence is not in itself a finding about the gene and the disease. The quoted sentences say what the papers report.
hyperlipidemia (1 paper, 2022). "In addition, significant upregulation was observed in DPPA5, DNM3OS, OR2T6, OR8H1 in four complications including neuropathy, ketoacidosis, hyperlipidemia and PCOs (p < 0.01) (Boxplots 8C, 8D, 8F,8H, respectively)." (PMID 36175575, 2022).
tumor (1 paper, 2020). "For example, OR8B8 and OR8H1 were exclusively detected in malignant breast epithelial cells, whereas OR1A1 and OR2M3 activation were observed in 11 and 10 different tumor types respectively, suggesting a distinct mode of expression regulation." (PMID 32917933, 2020).
OR8H1 also shares sentences with these, for which no sentence is quoted: cancer (1 paper); neuropathy (1).